CXCL11 (C-X-C motif chemokine ligand 11)
Diseases named in the same sentence as CXCL11 in open-access papers (continued):
Sharing a sentence is not in itself a finding about the gene and the disease.
tumor (continued). "Elevated serum levels of CXCL10, along with CXCL9 and CXCL11, are linked to poorer prognosis in MM patients, indicating a possible role for CXCR3 ligands in the tumor-promoting processes of MM." (PMID 40940985, 2025). "Considering the individual loadings on PC2 and PA, we found that patients who engaged in moderate PA had lower levels of CXCL9, CXCL10, and CXCL11, known pro-inflammatory chemokines involved in immune cell migration and tumor progression." (PMID 40510182, 2025). "This is characterized by enhanced expression of pro-inflammatory cytokines such as IFN-γ, which can also stimulate the secretion of chemokines (e.g. CXCL9, CXCL10, and CXCL11) to amplify the anti-tumour immune response." (PMID 40510180, 2025). "Comparable results were observed when CAR-T cells were used in combination with oncolytic vaccinia virus expressing CXCL11, a potent chemokine that draws T cells to tumor locations." (PMID 41024300, 2025). "This study confirms that SFV increases the expression of T-cell chemoattractant genes Cxcl9, Cxcl10, Cxcl11 and immune checkpoint molecule gene Cd40, promoting anti-tumour immunity." (PMID 40547518, 2025). "T-cells regulatory (Tregs), M0 macrophages, and M1 macrophages are co-owned by CXCL10 and CXCL11, suggesting that they can provide help in tumor immunotherapy of PAAD." (PMID 40129606, 2025). "CXCR3 ligands, such as CXCL9, CXCL10, and CXCL11, are mainly produced by monocytes, endothelial cells, and tumour cells and are crucial for regulating anti-tumour immunity." (PMID 40361472, 2025). "Compared to the control group, combination treatment significantly increased the expression of Ifng, Tnf, Gzmb, Cxcr3, Cxcl11 and Ccl19 in the tumor, suggesting a more inflammatory TME." (PMID 39816690, 2025). "Our study has detailly demonstrated the synergistic mechanism of CXCL10 and CXCL11 in the ELR-negative CXC chemokines gene family in the tumor microenvironment and immune infiltration of PAAD." (PMID 40129606, 2025). "We found that butyrate promoted CXCL11 production in tumor cells by enhancing H3K27ac and H3K9ac enrichment, thereby increasing chromatin accessibility at CXCL11 enhancer regions." (PMID 40576244, 2025). "In the meantime, Plac1+ tumor cells shape a Treg‐related immunosuppressive microenvironment via CXCL11/CXCR3 and PVR/TIGIT, which in turn activates the tumorigenic signaling of Plac1+ tumor cells via LTA/LTBR and forms a reciprocal protumor loop." (PMID 40056047, 2025). "For example, how Plac1 expression enhances caveolae‐related gene upregulation, and how Plac1+ tumor cells secrete higher concentrations of CXCL11 and express higher levels of PVR." (PMID 40056047, 2025). "Significant increase in CAR-T influx and infiltration into the tumor due to CXCL11 secretion, transforming a “cold” tumor into a “hot” one." (PMID 41294877, 2025). "In HNC, CXCL11 promotes tumor angiogenesis and epithelial–mesenchymal transition (EMT), aiding in metastasis and immune evasion through JAK/AKT and MMP7 activation." (PMID 40606440, 2025). "After 48 hours of butyrate stimulation, the enhancer region of CXCL11 was significantly activated in tumor cells, accompanied by notable enrichment of H3K9ac and H3K27ac histone modifications." (PMID 40576244, 2025). "Hetero-oligomerization with CXCR4 induces negative binding cooperativity—CXCL12 binding to CXCR4 suppresses CXCL11-mediated CXCR3 activation, a mechanism implicated in tumor immune evasion." (PMID 40786052, 2025). "Further analysis showed increased production of proinflammatory interleukins such as IL‐1β and IL‐16 and accumulation of various chemotactic agents, including CCL3, CCL4, CCL5, CXCL9, CXCL10, and CXCL11, in the tumor tissue." (PMID 41221154, 2025). "For instance, CXCR3, a receptor for chemokines CXCL9, CXCL10, and CXCL11, is more highly expressed in tumor tissues than in normal tissues." (PMID 39940842, 2025).
tumor (continued). "MTAP-deficient cancer cells showed impaired induction of key chemokines, CXCL9, CXCL10, and CXCL11, particularly in response to immune cell interaction, thereby contributing to the development of an immunosuppressive “cold” tumor microenvironment." (PMID 41246302, 2025). "Conditioned media from CXCL10- and CXCL11-expressing tumour cells significantly enhanced CAR T cell migration compared with media from control tumour cells using two distinct transwell migration assays." (PMID 41366257, 2025). "The enhancer of CXCL11 with reshaped chromatin accessibility partially overlapped with H3K9ac- and H3K27ac-enriched targets in butyrate-treated tumor cells." (PMID 40576244, 2025). "In cancer cells, autocrine CXCR3 signaling promotes metastasis and growth through AKT signaling, while CXCL9 and CXCL11 can inhibit tumor growth by facilitating immune cell infiltration." (PMID 39940842, 2025). "CXCL9, CXCL10, and CXCL11 interact with CXCR3 on tumor cells, immune cells, and vascular endothelial cells, influencing tumor growth, immune cell activity, and blood vessel formation." (PMID 40362215, 2025). "EC-C4 highly expressing DPP4 interacted with TAMs expressing chemokines CXCL10 and CXCL11, especially CXCL11+ TAMs, thereby inhibiting their anti-tumor immune response." (PMID 39232806, 2024). "Among these factors, chemokine CXCL11 caught our particular interest, because it has recently been shown, that CXCL11 is involved in tumor lymphatic cross talk and the regulation of checkpoint molecule PD-L1 (CD274) in cancer tissues." (PMID 38609887, 2024). "CXCL9, CXCL10, and CXCL11 are mainly secreted by myeloid lineages and tumor cells in the TME responding to IFN-γ, and this process is synergistically enhanced by TNF-α." (PMID 39076974, 2024). "The study demonstrated that combining CXCL11 with oAd within the tumor environment led to a sustained anti-tumor response." (PMID 39055561, 2024). "Analysis of the MDMs demonstrated that IFNG neutralization diminished induction of CXCL9, CXCL10 and CXCL11 gene expression in MDMs in both tumor model systems." (PMID 39414902, 2024). "RT-qPCR was employed to detect the mRNA levels of these chemokines in tumor tissues of our exercise models, confirming that Ccl5, Cxcl10, Cxcl9, and Cxcl11 were significantly increased in Ex mice compared to the Ctrl group." (PMID 38622609, 2024). "CXCR3-CD8+ T cell treatment significantly suppressed tumor growth by harnessing chemotaxis via the CXCR3/CXCL11 axis in 4T1 mouse models." (PMID 39543650, 2024). "In a comprehensive analysis of various cancer types, it was found that the expression of CXCL11 in tumor tissues is significantly higher than in normal tissues in most cancers." (PMID 38791448, 2024). "In the tumor microenvironment, CXCL11 is renowned for its multifunctionality, including inhibiting angiogenesis, affecting the proliferation of various cell types, and promoting the migration of certain immune cells." (PMID 38791448, 2024). "The upregulated genes in PTCL‐TBX21 included Th1‐related genes, including CXCR3, CD38, INFG, CXCL9, CXCL11, IL27, and genes associated with tumor immunity, such as CD274 (PD‐L1), LAG3, and IDO1." (PMID 38234210, 2024). "In the context of ICIs, these drugs are thought to act primarily on T cells, stimulating them to secrete IFN-γ, which in turn reduces endothelial VEGFA and increases the levels of CXCL-9, CXCL-10, and CXCL-11, contributing to tumor vascular normalization." (PMID 39850892, 2024). "CXCL4, CXCL10, and CXCL11 are known to inhibit angiogenesis and cell proliferation, thus targeting the angiogenic nature of the tumor microenvironment." (PMID 38339062, 2024). "The levels of CXCL10, CXCL9, and CXCL11 in the tumor correlates with the concentration of intratumoral cytotoxic lymphocytes (CTLs) and reduced tumor angiogenesis." (PMID 38726320, 2024).
tumor (continued). "Previous mouse models have shown that activation of TRAIL can lead to the activation of RIPK1, thereby inducing inflammatory responses and driving cell death, explaining the anti-tumor role of CXCL11+ TAMs by eliminating tumor cells through TNFSF10-RIPK1." (PMID 39232806, 2024). "Upregulation of CXCL10 in the HL_HPS_R tumor and upregulation of CXCL11 in the HL_HPS_L tumor seem relevant since they act as key immunological chemoattractant during inflammatory responses." (PMID 39339213, 2024). "On the other hand, a recent study found that miR-206, which targets CXCL11 as a tumor suppressor in PCa, negatively affected PCa cell growth and motility and delayed the cell cycle." (PMID 38745115, 2024). "As well, VV.CXCL11 significantly enhanced the anti-tumor efficacy of recruited T-cells as compared to the direct delivery of CXCL11 by CAR-T cells." (PMID 38558795, 2024). "Tumors of CXCR2 KO mice had elevated CXCL13 levels to recruit B cells and B cell-derived CXCL11 in turn attracted CXCR3+ T cells into the tumor." (PMID 38786066, 2024). "CXCL11 plays a significant role in modulating the tumor microenvironment and influencing the efficacy of cancer immunotherapy." (PMID 38791448, 2024). "The extensively diffusion of this cytokine alters the tumor microenvironment through the induction of CXCL9, CXCL10, and CXCL11, which recruit effect immune cells such as natural killer (NK) cells, T cells, monocytes, and others to the tumor site." (PMID 39080467, 2024). "In the present study, we constructed cells stably expressing the three IFN-inducible chemokines CXCL9, CXCL10, and CXCL11 in a mouse model and transplanted them into nude mice to investigate their anti-tumor effects." (PMID 37218983, 2023). "Analysis of DEGs revealed an upregulation of STAT1, STAT4, and CXCL11, indicating the activation of anti-tumor and immunomodulatory pathways." (PMID 37842640, 2023). "The CXCL9- and CXCL11-expressing cell lines significantly suppressed tumor growth on day 11 post-inoculation compared to that by the Vector, and this suppression was observed until day 18 (p < 0.05)." (PMID 37218983, 2023). "Further studies are required to determine the anti-tumor mechanisms of CXCL9- and CXCL11-expressing tumor tissues in nude mice." (PMID 37218983, 2023). "CXCR3/CXCL9/CXCL10/CXCL11 axis leads to recruitment of tumor-promoting immune cells, including TAMs, T cells, etc., thus favoring tumor growth and metastasis." (PMID 37818357, 2023). "CXCL9 and CXCL11 are key chemokines for the trafficking of effector T cells into the tumour and are secreted by macrophages and stromal cells in response to IFN-γ secreted by T-cells." (PMID 37013636, 2023). "The secreted CXCL9, CXCL10 and CXCL11 interact with tumour cells to induce cell death, such as apoptosis and attract adaptive immune cells leading to anti‐tumour immunity." (PMID 37170733, 2023). "The expression levels of CXCL9 (P = 0.0201), CXCL11 (P = 0.0385), and CXCL13 (P = 0.0288) were significantly associated with tumor stage." (PMID 36798787, 2023). "In this study, we established SCCVII cells stably expressing the IFN-inducible chemokines CXCL9, CXCL10, and CXCL11 and transplanted the cells into the backs of nude mice to investigate their anti-tumor effects." (PMID 37218983, 2023). "In one study, VACV expressing CXCL11 delivered intratumorally induced the aggregation of T cells in tumor tissues and increased the survival of tumor-bearing mice." (PMID 37631987, 2023). "The oncolytic adenoviruses infected tumor cells and induced apoptosis, while CXCL11 acted as a chemoattractant for CAR T cells, activated T cells, and NK cells, promoting their infiltration into GBM." (PMID 38104126, 2023). "We also found that abnormal expression of CXCL9 (P = 0.0201), CXCL11 (P = 0.0385), and CXCL13 (P = 0.0288) was closely associated to tumor stage, and the expression of CXCL9, CXCL11, and CXCL13 decreased with the increase of stage." (PMID 36798787, 2023).
tumor (continued). "Research has shown that chemokine ligands CXCL10 and CXCL11 have anti-angiogenic properties and can effectively inhibit tumor progression." (PMID 36969851, 2023). "Further, CXCL9 was positively related to CCL4, CCL5, CXCL10, and CXCL11 in UCEC, which are associated with DC, NK, and T cell recruitment and play an essential role in suppressing tumor growth and improving prognosis." (PMID 36845675, 2023). "Consistent with the in vitro cell experiments, we observed that PTP 9 and anti-PD-1 cotreatment induced a significant increase in tumor expression of Cxcl11, Ccl5, Stat1, Stat3, Tap1, Irf1, Casp8, and Pdl1, compared with anti-PD-1 treatment alone." (PMID 36968224, 2023). "Upregulation of several chemokines, including CCL3, CCL5, CCL22, CXCL9, CXCL10, and CXCL11, has been described to play different roles with effects depending on tumor type and other TME factors." (PMID 36831435, 2023). "Of note, circUBAP2 depletion reduces murine tumor migration and lung metastasis, whereas simultaneous blockade of miR-4756 antagonizes this suppression, indicating the significance of the CXCL11-circUBAP2/IFIT1/3 axis in HCC malignancy." (PMID 36708970, 2023). "As an autocrine signal, CXCL9, CXCL10, or CXCL11 activates the chemokines produced by the tumor through CXCR3A on cancer cells and further recruits immune cells to create an immune microenvironment that promotes tumors." (PMID 35992864, 2022). "IFN-γ-inducible CXCL9, CXCL10 and CXCL11 are chemokines for cytotoxic T cells, which attract more cytotoxic T cells to infiltrate into tumor tissues and exert anti-tumor effects." (PMID 35300424, 2022). "Similar results were accrued when CAR-T cells combined with oncolytic vaccinia virus (VV) expressing CXCL11 (a potent chemokine that attracts T cells to the tumor sites)." (PMID 36419058, 2022). "Through the autocrine production of CXCL11, tumor cells can regulate their own directional movements and influence processes such as cancer cell proliferation, angiogenesis, and immune evasion." (PMID 36478746, 2022). "A study strongly suggested that the secretion of SASP by senescent endothelial cells promotes the invasive behavior of tumor cells via CXCL11 targeting the tumor microenvironment." (PMID 36275644, 2022). "The chemokine CXC motif receptor 3 (CXCR3), the CXCL9, CXCL10 and CXCL11 specific receptor, participates in the tumor migration, invasion, angiogenesis and immunity and are mainly expressed on monocytes, effector T cells, NK lymphocytes and cancer cells." (PMID 36030223, 2022). "In summary, we identified SPATA2 and CYLD as novel regulators of T/NK cell-attracting chemokines CXCL9, CXCL10, CXCL11 in tumor cells." (PMID 36531014, 2022). "In the neoadjuvant setting of muscle-invasive bladder cancer, tumor biopsies before treatment revealed that the CXCL11 abundance correlated with high TILs." (PMID 36429101, 2022). "It was also shown that CXCL11 delivering to the tumor site by a VV is more efficient in tumor cell killing in vivo than secreting CXCL11 by CAR-T cells." (PMID 36419058, 2022). "Data on combined effects of CXCL12 and CXCL11 on the tumor microenvironment are at present unavailable." (PMID 36539774, 2022). "Among the chemokines, the type-1 chemokines CXCL9, CXCL10, and CXCL11 contribute to the inhibition of angiogenesis and tumor progression." (PMID 36146629, 2022). "Among the INFA response-enriched genes, SAMD9, CXCL10 and CXCL11 genes overlapped in the exosomes; tumor tissue overlapped from the core enrichment genes." (PMID 36230645, 2022). "CXCL11-armed oncolytic poxvirus i.p. injected into mesothelioma-bearing mice favors the CD8 T-cell accumulation in the tumor which is then responsible for an efficient antitumor immune response." (PMID 36429101, 2022). "Despite the established interaction between the CXCL12- and CXCL11-systems, combined effects of both chemokine systems on tumor growth and metastasis are still ill defined." (PMID 36539774, 2022).
tumor (continued). "We further conclude that CXCL12, CXCL11 alone or in combination exert anti-apoptotic effects only in distinct tumor cells." (PMID 36539774, 2022). "All tumor cells showed statistically significant migratory responses to CXCL11 at concentrations as low as 1 ng/ml, whereas with CXCL12 at 1 ng/ml statistically significant migratory responses only occurred with A549 and A767 cells." (PMID 36539774, 2022). "A further analysis in a cohort with localized and locally advanced colon cancer confirmed that patients having high CXCL11 in the tumor tissue lived longer." (PMID 36429101, 2022). "Although our previous work revealed that A549, DLD-1 and MDA-MB-231 cells express CXCR3B, we obtained no indication for the involvement of CXCR3B in the migratory responses of these tumor cells to CXCL11." (PMID 36539774, 2022). "Although CXCL11 has anti-tumour activity via the recruitment of innate and adaptive immune cells at the site of tumour, some colorectal tumours express CXCR3 receptors that function as a metastatic mediator." (PMID 36059680, 2022). "In studies of tumor angiogenesis in colorectal cancer, CXCL11 and CXCL12 have been shown to have a reciprocal regulatory role." (PMID 35770088, 2022). "While CXCL11 is a chemokine that mainly attracts activated T cells, allowing them to migrate to tumour sites and suppress tumours, CXCL5 and CXCL1 are chemokines with chemotactic and neutrophil-activating functions." (PMID 35740353, 2022). "A Western blot analysis of the removed tumor tissue showed that the expression of CXCL11 and PD-L1 decreased synchronously after EphA2 was knocked down." (PMID 36478746, 2022). "Our present demonstration that depending on the tumor cell type, a combination of CXCL12 and CXCL11 either allows for pro- or anti-tumor activity put caution on ongoing efforts to establish chemokine receptors as therapeutic targets in cancer." (PMID 36539774, 2022). "In the present work, we have analyzed CXCL12 and CXCL11 for combined effects on migration, invasion, proliferation, and cytostatic-induced apoptosis of the human tumor cells, A549, A767, A772, DLD-1, and MDA-MB-231." (PMID 36539774, 2022). "CXCL11 limits T cell effector functions through induction and/or recruitment of Treg, and it is capable of binding to CXCR7, commonly associated with tumor cells growth and invasiveness." (PMID 35361879, 2022). "IFN-γ-inducible CXCL9, CXCL10 and CXCL11 are chemokines for the activation of cytotoxic T cells, which attract more cytotoxic T cells to infiltrate into tumor tissues and exert anti-tumor effects." (PMID 35300424, 2022). "IFN-γ-inducible CXCL9, CXCL10, and CXCL11 are chemokines attracting cytotoxic T cells to infiltrate into tumor tissues and exert anti-tumor effects." (PMID 35300424, 2022). "The presence of docetaxel induces a higher expression profile of high mobility group box 1 (HMGB1) from tumor cells which in turn induces the expression of CXCL11 through NF-κB activation." (PMID 35634281, 2022). "Our previous work revealed that CXCL12 and CXCL11 promote tumor cell migration with equal potency and further demonstrated that in most tumor cells these migratory responses involve either CXCR7 alone or CXCR7 in combination with another chemokine receptor." (PMID 36539774, 2022). "CXCL9 and CXCL11 recruit CXCR3+ T cells to the skin and overexpressed in rashes, higher CXCL9 and CXCL11 expression in macrophages had more CD8+ T cells in the tumor microenvironment." (PMID 36479091, 2022). "CXCL11 production by CAR T cells themselves likely had little effect due to the inability of CAR T cells to establish localised gradients at tumour sites." (PMID 35205725, 2022). "By releasing an extracellular regulator, galectin-3, tumor cells are capable of blocking interferon gamma (IFN-γ) in the TME followed by impeding chemokines CXCL9, CXCL10, and CXCL11 leading to obstructed T-cell recruitment into the tumor bed." (PMID 35053449, 2022).